ITGA2 (integrin subunit alpha 2)
Diseases named in the same sentence as ITGA2 in open-access papers (continued):
Sharing a sentence is not in itself a finding about the gene and the disease.
tumor (continued). "For ITGA2, SLC1A5, TIAM1, TNIK, and ABTB2, several studies showed that their high expression played a significant role in promoting tumor cell growth and inhibiting cell apoptosis from chemotherapy in different kinds of cancers." (PMID 35267472, 2022). "By using an immunofluorescence assay, we detected the colocalization of tumor cell–expressed ITGA2 and fibroblast-expressed FN1, indicating a role of ITGA2 and its ligand in regulating tumor cell–fibroblast interactions." (PMID 35719923, 2022). "In this work, the data mining of PDAC scRNA-seq data revealed that ITGA2, ITGA3, ITGB4, and ITGB6 were dominantly expressed in tumor cells." (PMID 35719923, 2022). "After that, we mapped the expression level of the pair co-expressed between post-treatment tumors and tumor stroma (COL3A1; ECM ligand and ITGA2; ECM receptor) on the tissue section." (PMID 36505794, 2022). "Integrin alpha 2 (ITGA2) has been recently reported to be an oncogene and to play crucial roles in tumor cell proliferation, invasion, metastasis, and angiogenesis." (PMID 35193647, 2022). "Key TGFB activators include integrin proteins, 4 of which (ITGA2, ITGA3, ITGB1, ITGB3) displayed increased expression in the HCC tumor cells (Log2 fold change = −6.16, −5.56, −2.32, and −4.35, respectively)." (PMID 33995488, 2021). "In conclusion, miR-145-5p is a tumor suppressor in CC and can inhibit the expression of CXCL1 and ITGA2." (PMID 34860147, 2021). "Integrin and adhesion related genes including ITGA2, ITGA6, and ICAM5 were changed by −6.12, −2.75, and −5.77-fold, respectively, comparing tumor to parent cells." (PMID 33808801, 2021). "Based on these results, ITGA2, ITGAV, and GPC1 were used to isolate tumor-derived EVs in subsequent experiments." (PMID 34948417, 2021). "Results illustrated that ITGA2, ITGA3, ITGA4, ITGA6, ITGA11, and ITGAV transcripts were increased in ESCC tumour tissues (n = 95) compared with normal tissues (n = 11)." (PMID 34709754, 2021). "Differential methylation of the ITGA4, SFN, ITGA2, and PIK3R1 genes allowed the discrimination between normal and tumour tissue and correlated with patient survival." (PMID 34944974, 2021). "In the tumor cells, the dysregulation of UBE2CP3 will lead to the amplified dysregulation of miR-138-5p and ITGA2." (PMID 34274947, 2021). "We next verified the protein levels of the integrin α‐subunits suggested to be differentially represented between samples at the mRNA level, including ITGA2, ITGA3, ITGA4, ITGA6, ITGA11, and ITGAV using 10 paired (tumour and adjacent) ESCC patient tissues." (PMID 34709754, 2021). "Microarray database analysis collected from NCBI showed that tumor cells isolated from bone marrow have fewer copy numbers of ITGA2 and ITGB1 compared to primary tumor cells or circulating tumor cells." (PMID 34199096, 2021). "Results showed that ITGAV (10/10), ITGA2 (7/10), ITGA3 (8/9), ITGA4 (7/10), ITGA6 (7/8), and ITGA11 (7/9) protein levels were increased in tumour tissues compared with adjacent tissues." (PMID 34709754, 2021). "Therefore, we examined whether ascites-derived tumor cells (ATCs) as well as matched primary (OV) and metastatic tissues (OM) express ITGA2, and identified that 61.5% of patients-derived ATCs are E-cadherin and ITGA2 positive." (PMID 33026975, 2020). "Moreover, elevated ITGA2 expression positively correlates with the defined collagen gene set in The Cancer Genome Atlas (TCGA) (R = 0.32, p=1.2e-10) and GTEx (R = 0.34, p=1.9e-09) dataset suggesting a potential interaction between ITGA2+ tumor cells and enriched collagens in the premetastatic niche." (PMID 33026975, 2020). "Tumor size and weight were significantly reduced by 5-FU or ADR treatment in mice implanted with ITGA2-silenced GC cells." (PMID 32232000, 2020). "Consistent with the inhibition of cell proliferation by knocking down ITGA2 in human PDAC cells, Itga2 repression inhibited tumor growth in murine Panc02 cells in vivo." (PMID 31818309, 2019).
tumor (continued). "Due to ITGA2 upregulation and CD44 downmodulation after Maitake treatment, thus blocking tumor cell survival, metastasis, and arteriogenesis in tumoral MCF-7 cells." (PMID 29872510, 2018). "In comparison with the control group, except for miR-204-5p, the expression levels of ITGA2, FN1, ICAM1, CDH2, TIMP1, CLDN1, TNFRSF12A, miR-146b, and miR-222 were all up-regulated in the tumor group, consistent with the results of the bioinformatics analyses." (PMID 30414611, 2018). "After an encounter with CCR9lo tumour cells, genes involved in the positive regulation of the immune response, such as lymphotoxin alpha (LTA) and integrin alpha-2 (ITGA2), were over-expressed in CTL." (PMID 26861383, 2016). "In the present study, low signal levels of ITGA2–UEA and ITGB4–MAA assays from serum were significantly associated with both tumor recurrence and negative radiotherapy response." (PMID 40287842, 2025). "Furthermore, distinct molecular profiles were observed between tumor cells in tumor nests and in air spaces in STAS patients, which was highlighted by the elevated ITGA2 expression in the air spaces." (PMID 40786043, 2025). "PMC_2 marker (ITGA2) and fibroblast marker (VIM), were also markedly reduced in all treated groups, indicating lower PMC_2 and fibroblast infiltration, and their synergistic effect in disrupting the tumor-promoting microenvironment." (PMID 40976783, 2025). "Therefore, ITGA2–UEA is suggested to be a potential predictive biomarker for HNSCC radiotherapy response and tumor recurrence, but naturally, further studies including validation by functional analysis would be needed to confirm its role as a biomarker." (PMID 40287842, 2025). "RNA-based microarray analysis of GBM cells confirmed coagulation-related changes, including upregulation of platelet adhesion marker ITGA2, and downregulation of THBS1, a regulator of clotting, platelet aggregation, extracellular matrix remodeling, and tumor invasiveness." (PMID 40885689, 2025). "Additionally, tumor adhesion and metastasis-promoting molecules, including ITGB4 and ITGB8, whereas ITGA1 and ITGA2 were downregulated in ST6GAL1-knockdown cells." (PMID 39937175, 2025). "Between tumor tissue and normal adjacent tissue, the correlation of glycovariants was very weak to weak, with the only exceptions being the moderate correlation between intratumoral ITGA6–UEA, ITGA2–UEA, and ITGA5–UEA from normal adjacent tissues." (PMID 40287842, 2025). "However, other HGs, especially collagen‐related genes, including COL1A1, COL1A2, ITGA2, and POSTN revealed slightly higher methylation in tumor tissue than in normal tissue." (PMID 38639039, 2024). "To investigate whether VIRMA exerts its tumor-promoting function through upregulating ITGA2, ITGA5, and NTRK1 expression, we performed in vitro functional experiments by overexpressing ITGA2, ITGA5, or NTRK1 in VIRMA-silenced NPC cells." (PMID 37028765, 2023). "It inhibited the proliferation and migration of tumor cells by downregulating CXCL1 and ITGA2." (PMID 37745305, 2023). "Finally, we found that after inhibiting SDC1 and ITGA2 expression in BxPC-3 and MIA-PaCa2 cell lines, the tumor size was significantly reduced, showing a potential therapeutic effect." (PMID 37907515, 2023). "We did not observe a significant modulation of cell proliferation, neither of tumor growth after silencing of ITGA2 in our PANC-1R model." (PMID 36765586, 2023). "Furthermore, we evaluated the possible link between the ECMGs and the tumor stage of PAAD, and 8 ECMGs (i.e. FN1, LAMA3, ITGB6, ITGB4, ITGA2, LAMC2, COL11A1, LAMB3) were detected to be significantly associated with tumor stage." (PMID 36311789, 2022). "ITGA2 overexpression is essential for tumor development, metastasis, and motility, and this molecule triggers the overexpression of the STAT3 signaling pathway, thus promoting tumor progression." (PMID 36245988, 2022).
tumor (continued). "We found that differential methylation of the ITGA4, SFN, ITGA2, PIK3CD, and PIK3R1 genes allowed the discrimination between normal and tumour tissue evidencing that all 12 CpGs identified were good to excellent diagnostic biomarkers with AUC > 0.8 in two independent cohorts." (PMID 34944974, 2021). "We observed an overall high percentage of positive ITGA2 cytoplasmic (72.5%) and membranous staining (66%) of tumor cells (total n = 200 EOC patients) without differences for histological grade, FIGO stage, and subtypes." (PMID 33026975, 2020). "Flow cytometry analysis of tumors excised from the mice at the end of treatment revealed that the populations of tumor-infiltrated CD45+CD8+ T-cells and CD45+CD4+ T-cells increased after Itga2 knockdown, while the population of CD11b+Gr1+ myeloid cells decreased." (PMID 31818309, 2019). "In the present study, two genes ITGA2 and MMP7 were screened from DEGs as hub genes by using a series of bioinformatics methods, and they could discriminate normal samples and tumor samples." (PMID 30428899, 2018). "Indeed, integrins gene expression in the clinical ESCC tumor tissues show significant higher levels of integrin α-1 (ITGA1), ITGA2, ITGA5 and ITGB1 mRNA compared to normal tissue from the same patient." (PMID 30241395, 2018). "Together, these findings highlight ITGA2’s central role within the tumor microenvironment and multifactorial signaling network: not only is it finely regulated upstream, but it also extensively engages with key pathways such as PD-L1 and TGF-β, potentially collectively mediating drug resistance." (PMID 40940943, 2025). "As a curious side note, ITGA2 and ITGB1 assays with AAL and UEA lectins were significantly associated with cardiovascular disease in adjacent macroscopically normal tissue, but not in tumor tissue." (PMID 40287842, 2025). "In addition, hBM-MSC-Exo and hUC-MSC-Exo containing tumor-suppressive miRs (miR-3940-5p/miR-22-3p/miR‐16‐5p) have been shown to suppress proliferation, migration, and invasion of CRC cells via regulation of RAP2B/PI3K/AKT signaling pathway and ITGA2/ITGA6." (PMID 35365226, 2022). "Furthermore, the expression of HOXD3 and ITGA2 in LV‐shHOXD3 tumours was lower than that in control tumours, and the expression of HOXD3 and ITGA2 was notably decreased in the HOXD3‐downexpressing treated tumours as compared with that in the control treated tumours at protein levels." (PMID 32557953, 2020). "By analyzing R2: Genomics Analysis and Visualization Platform database, we found that ITGA2 is significantly upregulated in human GBM tumor tissues and high ITGA2 expression has a negative impact on GBM patient survival, suggesting ITGA2 as a promising therapeutic target for GBM." (PMID 30996239, 2019). "This strategy may direct the therapeutic activity of the anti-ITGA2 antibodies to tumor lesions, but not the normal tissues." (PMID 29743821, 2018). "Besides FLNC, ITGA2, COL1A1 and COL11A1 were tumor invasion and metastasis-related proteins." (PMID 27626164, 2016). "Interestingly, ITGA2 and ITGB1 assays with AAL and UEA lectins were significantly associated with cardiovascular disease in adjacent macroscopically normal tissue but not in tumor tissue." (PMID 40287842, 2025). "Indeed, the tumor cores (L and LB) were found to express numerous pEMT genes at significantly greater levels than the TME, including the laminins (LAMC1, LAMC2, LAMA3), integrins (ITGA2, ITGB1, ITGAV), and inflammatory and neutrophil-attracting chemokines (CXCL8, CXCL1)." (PMID 36216799, 2022). "E2F7 cooperated with CBFB-recruited RUNX1 in a non-canonical manner to transactivate ITGA2, ITGA5, and NTRK1, strengthening Akt signaling-induced tumor-promoting effect." (PMID 37028765, 2023). "Tr1 lymphocytes have been detected in both tumor tissue and peripheral blood of EBV+ cHL patients, and configure a regulatory subset lacking Foxp3, but usually expressing integrin subunit alpha 2 (ITGA2) and lymphocyte-activation gene 3 (LAG3)." (PMID 33327433, 2020).
tumor (continued). "The results showed that the expression levels of ITGA2, ITGB6, LAMA3, LAMB3, and LAMC2 are significantly correlated with the tumor stage of PAAD patients, while the expression levels of COL1A2 are not correlated with the tumor stage of PAAD patients." (PMID 35899199, 2022). "Suggestively, the functional interaction between PLA2R1 and β1 integrin may favour ITGA2 in LNCaP cells due to the lack of ITGA1-expression resulting in a decreased tumour growth and tumour-suppressive role of PLA2R1 in vivo." (PMID 30542512, 2018).
cancer (151 papers, 1998 to 2025). A tumor composed of atypical neoplastic, often pleomorphic cells that invade other tissues. "Integrins, particularly integrin α2 (ITGA2), have been associated with cancer progression and drug resistance." (PMID 41008552, 2025). "In PDAC, the expression of integrin α2β1 is detected in well-differentiated tumors, whereas ITGA2 tend to undergo epitope loss or alter subcellular localization during the cancer progresses." (PMID 39568561, 2024). "The result pinpointed ITGA1 and ITGA2 as the two genes with the highest proportions of deep loss in PCa compared to other cancer types." (PMID 38169150, 2024). "ITGA2 (encodes integrin α2 subunit, CD49b) plays a role in cancer cell migration, cancer stemness and differentiation." (PMID 36231068, 2022). "Because ITGA2 is critical for promoting cancer cell progression in vivo and in vitro, we employed RNA-seq analysis to identify the underlying mechanism of how ITGA2 regulates carcinogenesis." (PMID 31818309, 2019). "Given that ITGA2 promoted PD-L1 expression in cancer cells, we wanted to identify the underlying mechanism of the process." (PMID 31818309, 2019). "We investigated the specific biological role of ITGA2 in cancer in this research, and our results revealed that ITGA2 was abnormally overexpressed and significantly associated with unfavorable survival rates in several malignant tumors." (PMID 31818309, 2019). "Recent studies have indicated that ITGA2 C807T polymorphism was associated with increased risk of various cancers namely colorectal and breast carcinoma." (PMID 29121049, 2017). "The loss of ITGA2 in cancer cells was associated with metastatic behavior in hepatocarcinoma, colon carcinoma, and rhabdomyosarcoma." (PMID 26258411, 2015). "Here, we found that the reduction degree at protein level was more than that at mRNA level, suggesting that other regulatory mechanism participates into the loss of ITGA2 expression in primary cancers, in addition to the regulation at transcription level." (PMID 26258411, 2015). "Serving as a therapeutic target, ITGA2 is found to be overexpressed in certain cancer cell lines and tumor tissues, which may cause the promotion of cancer aggression." (PMID 35186766, 2022). "Loss of ITGA2 in cancer cells is associated with metastasis in breast and colon carcinoma." (PMID 29121049, 2017). "The ITGA2 level was lost in primary cancers; however, the mechanism of ITGA2 loss is still unclear." (PMID 26258411, 2015). "The loss of ITGA2 plays an important role in cancer metastasis in several solid cancers." (PMID 26258411, 2015). "Following that, we investigated ITGA2's influence on tube formation by human lymphatic endothelial cells (HLECs), a crucial step in cancer LNM." (PMID 39634132, 2025). "Our findings demonstrate that ITGA2 is enriched in cancer cells with high stemness and regulates the stemness of OSCC." (PMID 40316546, 2025). "Most notably, many of these early response alterations in the cancer cells are known pro‐angiogenic transcripts, including ITGA2, CLDN12, SMAD7, MET, KLF4, ID3 and ID1." (PMID 40116596, 2025). "Integrin alpha 2 (ITGA2) plays critical roles in various tumorigenic processes via cancer-related signaling pathways." (PMID 39634132, 2025). "In summary, ITGA2 plays a pivotal role in digestive cancers, exerting influence on cancer initiation, metastasis, resistance to chemotherapy, and genomic instability." (PMID 39568561, 2024). "Studies have indicated that cancer stem cells (CSCs) display heightened expression of ITGA2 and ITGB1, which interact with EGFR to initiate the ERK/Akt-mediated survival pathway, thereby facilitating CSCs in evading anoikis." (PMID 39568561, 2024). "Along with other types of cancers, upregulation of ITGA2 was reported in PC, which is responsible for metastasis and chemoresistance of PC." (PMID 38639039, 2024).